ADAM10 (ADAM metallopeptidase domain 10)
Diseases named in the same sentence as ADAM10 in open-access papers (continued):
Sharing a sentence is not in itself a finding about the gene and the disease.
adenoma (2 papers, 2018 to 2025). A neoplasm arising from the epithelium. "ADAM10-mediated Notch signalling is also implicated in GI cancers, with roles in adenoma formation and stem cell maintenance, and antibodies targeting ADAM10 in colorectal (CRC) and GBM models inhibited tumour growth and impacted the tumour microenvironment." (PMID 41226720, 2025). "ADAM10 deletion in APC biallelic loss models markedly reduced adenoma formation both in the small intestine and colon and improved animal survival; activated NOTCH rescued the ADAM10-deficient phenotype." (PMID 29652830, 2018).
Allergy (2 papers, 2015 to 2018). An allergy is an immune response or reaction to substances that are usually not harmful. "Allergic patients and allergy-prone Th2 mice have increased expression of ADAM10 on B-cells and increased soluble CD23 and IgE levels in plasma." (PMID 30013551, 2018). "Our results are an advance in elucidating the key role of ADAM10 in allergy pathogenesis, and provide a novel approach to the diagnosis, prognosis, and treatment of atopic disorders." (PMID 25933166, 2015). "Taken together, it is critical to consider both innate B cell levels of ADAM10 and ADAM17 as well as Th context when determining host susceptibility to allergic disease." (PMID 25933166, 2015). "ADAM10 contributes to allergic disease being the principal sheddase of CD23, the low affinity IgE receptor, which promotes IgE production and is increased in allergic patients’ sera." (PMID 25933166, 2015). "Since B cell levels of ADAM10, ADAM17, and TNF mRNA expression were clearly different in control and allergic patients; and allergy is a Th2-dominated disorder; we sought to confirm our results in classic Th1 and Th2 prone mouse strains." (PMID 25933166, 2015). "ADAM10, as the sheddase of the low affinity IgE receptor (CD23), promotes IgE production and thus is a unique target for attenuating allergic disease." (PMID 25933166, 2015). "We investigate specifically whether intrinsic differences in B cell ADAM10 levels, independent of Th bias, regulates allergy induction and severity and whether this regulation is associated with modulation of B cell ADAM17 and TNF and associated changes in secondary lymphoid follicular architecture." (PMID 25933166, 2015).
aneurysm (2 papers, 2017 to 2025). Bulging or ballooning in an area of an artery secondary to arterial wall weakening. "ADAM10 plays a vital role in the formation of aneurysm, but whether miRs modulate its activity during AAA formation is totally unknown." (PMID 28357407, 2017).
aortic aneurysm (2 papers, 2024 to 2026). A ruptured aneurysm located in the wall of the proximal portion of the descending aorta proceeding from the arch of the aorta. "Accordingly, for aortic aneurysm a lower degree of correlation of ADAM10 with sVEC was found (r = 0.4464, 95%-CI: 0.2393–0.6147, p < 0.0001)." (PMID 39501015, 2024). "Here we investigated the specificity and linkage of sVEC production with ADAM10/17 and TNF-α, both in vitro and in patients with aortic aneurysms and dissections, comparing the findings with those from patients with carotid stenosis and varicosis." (PMID 39501015, 2024). "As patients with aortic aneurysms and dissections each present with either specifically elevated TNF-α or ADAM10, the sVEC level in these patients, though not significantly different, could be influenced to varying degrees by TNF-α and ADAM10." (PMID 39501015, 2024).
Aortic dissection (2 papers, 2021 to 2024). Aortic dissection refers to a tear in the intimal layer of the aorta causing a separation between the intima and the medial layers of the aorta. "To figure out if the sVEC levels are influenced by TNF-a and ADAM10, as suggested by the in vitro data, we performed a simple linear regression analysis including all disease categories and separately for the aortic pathologies including aortic dissection and aneurysm." (PMID 39501015, 2024). "Although the ADAM10 concentration does not differ significantly between chronic and acute aortic dissection, sVEC appears to be regulated differently." (PMID 39501015, 2024).
Arthritis (2 papers, 2017 to 2024). Inflammation of a joint. "Expression levels of ADAM8 and ADAM10 in the synovial fluid correlate with the degree of joint inflammation and disease severity, respectively." (PMID 28260841, 2017). "Similar to ADAM10, knockdown of ADAM15 results in suppressed migration and invasion of FLS and silencing of ADAM15 in a rat model of CIA reduced the arthritis score and the extent of joint damage." (PMID 28260841, 2017).
B-cell chronic lymphocytic leukemia (2 papers, 2016 to 2025). "While ADAM10's direct involvement in chronic lymphocytic leukemia (CLL) is less defined, it is implicated in other B-cell malignancies." (PMID 40746920, 2025). "In contrast, ADAM10 expression remained non-significant in untreated Chronic Lymphocytic Leukemia (CLL) samples." (PMID 40746920, 2025).
benign prostate hyperplasia (2 papers, 2014 to 2025). "Moreover, in the prostate, the membranous ADAM10 expression was observed to be high in benign prostatic hyperplasia patient samples, and the nuclear translocation of ADAM10 coupled with the androgen receptor was involved in human PCa tumor growth and progression." (PMID 24520307, 2014).
breast invasive carcinoma (2 papers, 2021 to 2024). "Furthermore, a negative association between NME1 and ADAM10 protein levels was observed in 74 samples of breast invasive carcinoma in the TCGA database by mass spectrometry." (PMID 33918324, 2021).
cardiac hypertrophy (2 papers, 2013 to 2022). "Histopathological characterization in 6-month-old mice revealed no overt signs of cardiac hypertrophy or fibrosis when cardiomyocyte-specific ADAM10 knockout (KO) mice were compared to ADAM10fl/fl (WT) littermates." (PMID 36496449, 2022). "ADAM10 is responsible for the proteolytic release of the ectodomains of numerous protein substrates, including specific ligands of EGFR (epidermal growth factor receptor) regulating the subsequent EGFR-dependent signal transduction pathways involved in cardiac hypertrophy." (PMID 24206753, 2013).
cardiomyopathy (2 papers, 2021 to 2022). A disease of the heart muscle or myocardium proper. "We show that myocardial ADAM10 is distinctly upregulated in myocardial biopsies from patients with ischemia-driven cardiomyopathy." (PMID 36496449, 2022). "We found that myocardial ADAM10 is markedly upregulated in biopsies from patients with ischemia-driven cardiomyopathy." (PMID 36496449, 2022). "Since ADAM10 is crucial for the N-cadherin cleavage, the present research focused on elucidating the possible role of ADAM10 inhibition in DOX-induced cardiomyopathy." (PMID 34522779, 2021).
dilated cardiomyopathy (2 papers, 2021 to 2022). Cardiomyopathy which is characterized by dilation and contractile dysfunction of the left and right ventricles. "The present research was designed to examine the effects of disintegrin metalloproteinases 10 (ADAM10) on the doxorubicin (DOX)-induced dilated cardiomyopathy (DCM) and the mechanisms involved, with a focus on ADAM10-dependent cleavage of N-cadherin." (PMID 34522779, 2021). "To validate the translational relevance of the uncovered ADAM10 upregulation, we analyzed ADAM10 expression in tissue lysates from patients with ischemic (ICM) and dilated cardiomyopathy (DCM) or non-failing hearts (NF)." (PMID 36496449, 2022).
emphysema (2 papers, 2018 to 2020). "Notably, an ectodomain of GPNMB may be cleaved out by MMP-type protease ADAM10, known to promote emphysema of the lungs, and shed into circulation as a soluble, biologically active molecule with angiogenic properties." (PMID 32478378, 2020). "In total of the treated and control mice of 30 weeks of age, Lm was positively correlated with the CTF and ADAM10 levels, and pan-cytokeratin was negatively correlated with CTF, suggesting an involvement of CADM1 shedding in emphysema progression." (PMID 29892598, 2018).
esophageal cancer (2 papers, 2016 to 2022). A primary or metastatic malignant neoplasm involving the esophagus. "These considerations underscore the relevance of our finding that the release of HER-activating ligand in esophageal cancer is in fact induced by upregulated ADAM10." (PMID 26863569, 2016). "Using primary established HER2-overexpressing cultures and patient-derived xenograft models, we now reveal a novel resistance mechanism to trastuzumab in esophageal cancer: In response to trastuzumab, both HER3 and the metalloprotease ADAM10 are simultaneously upregulated." (PMID 26863569, 2016).
fragile X syndrome (2 papers, 2019 to 2022). A genetic syndrome caused by mutations in the FMR1 gene which is responsible for the expression of the fragile X mental retardation 1 protein. "Moreover, ADAM10 maturation is increased in a mouse model of Fragile X syndrome (FXS) that is used as a murine ASD model." (PMID 36232346, 2022). "In addition to the role of ADAM10 in AD, recent studies suggest that ADAM10 may contribute to other neurological diseases including fragile X syndrome, traumatic brain injury, and psychiatric disorders." (PMID 31114485, 2019).
glomerular diseases (2 papers, 2010 to 2017). "We detected elevated levels of ADAM10 in urine and in urinary vesicles of patients with glomerular diseases compared to healthy volunteers." (PMID 20070888, 2010). "Podocytes isolated from urines of patients with glomerular diseases express constitutively ADAM10." (PMID 28484521, 2017). "Therefore we analyzed urine and urinary vesicles isolated from healthy volunteers and patients with glomerular diseases for the expression of ADAM10 and L1 adhesion molecule." (PMID 20070888, 2010).
head and neck cancer (2 papers, 2021 to 2022). A primary or metastatic malignant neoplasm affecting the head and neck. "Treatment with silibinin, a plant-based flavonoid, upregulated miR-494 in head and neck cancer, which downregulated ADAM10 (a disintegrin and metalloprotease domain 10) and BMI1 (B lymphoma Mo-MLV insertion region 1 homolog), resulting in inhibition of tumor growth and self-renewal properties." (PMID 33578944, 2021).
Huntington disease (2 papers, 2022 to 2024). Huntington disease (HD) is a rare neurodegenerative disorder of the central nervous system characterized by unwanted choreatic movements, behavioral and psychiatric disturbances and dementia. "Recently, Cozzolino and co-workers performed an immuno-affinity purification-mass spectrometry (IP-MS) study of endogenous ADAM10 in the brains of wild-type and Huntington’s disease (HD) mice." (PMID 36140397, 2022).
hyperglycaemia (2 papers, 2023). "Decreased ADAM10 and increased CXCL16 protein expression could be a protective response for podocytes against hyperglycemia through the scavenging of oxidated LDL by CXCL16." (PMID 37513824, 2023).
injury (2 papers, 2021 to 2022). Damage inflicted on the body as the direct or indirect result of an external force, with or without disruption of structural continuity. "In traumatic brain injury, inhibition of Adam10 attenuated the upregulation of Mmp2 and Mmp9 expression." (PMID 35163191, 2022).
Insulin resistance (2 papers, 2015 to 2023). Increased resistance towards insulin, that is, diminished effectiveness of insulin in reducing blood glucose levels. "Our data showed an increase in active GSK3β in ECs after the insulin resistance, which was associated with a concurrent increase in VCAM1 and ADAM10 and 17 expressions." (PMID 37762417, 2023). "Since basal Akt activity phosphorylates and deactivates GSK3β, we hypothesized that insulin resistance likely led to an activation of GSK3β, which induced ADAM10/17 and VCAM1 expression." (PMID 37762417, 2023). "The activation of GSK3β in ECs after insulin resistance upregulates VCAM1 expression, and VCAM1’s ectodomain is cleaved by the metalloproteases ADAM10 and ADAM17, which also show increased expression in diabetic ECs." (PMID 37762417, 2023).
ischemic cardiomyopathy (2 papers, 2022 to 2025). Ischemic cardiomyopathy is a cardiomyopathy in which a weakness in the muscle of the heart due to inadequate oxygen delivery to the myocardium with coronary artery disease being the most common cause. "It has been reported that myocardial biopsies from patients with ischemic cardiomyopathy clearly show elevated expression of ADAM10, with cardiomyocytes and endothelial cells predominantly expressing ADAM10." (PMID 40508161, 2025).
lung diseases (2 papers, 2019 to 2022). "Thus, berberine is a potent anti-inflammatory drug that alleviates lung inflammation associated with ADAM10-mediated lung diseases." (PMID 35563195, 2022). "We also checked two other lung-disease-related proteases, MMP12 and ADAM10." (PMID 31562139, 2019).
malaria (2 papers, 2011 to 2019). Malaria is a serious and sometimes fatal disease caused by a parasite that commonly infects a certain type of mosquito which feeds on humans. "A recent study has shown ADAM10 to be essential for cell entry of Plasmodium falciparum due to its interaction with the malaria PfSUB2 enzyme." (PMID 21569301, 2011).
pemphigus (2 papers, 2021 to 2022). Pemphigus is a group of rare autoimmune diseases that cause blistering of the skin and mucous membranes (mouth, nose, throat, eyes, and genitals).This conditioncan occur at any age, but often strikes people in middle or older age. "Sheddases ADAM10 and ADAM17 are involved in the turnover of the desmosomal cadherin Dsg2 and ADAM10 has been shown to contribute to acantholysis in a murine pemphigus model." (PMID 35844545, 2022). "We addressed the role of the sheddases ADAM10 and ADAM17 in both keratinocyte adhesion and loss of cell adhesion in pemphigus in human keratinocytes." (PMID 35844545, 2022). "However, the protective effect of ADAM10 inhibition in pemphigus appears to be dependent on the autoantibody-profile of different pemphigus patients, which is in line with a previous study." (PMID 35844545, 2022). "ADAM10 has also been linked to acantholysis in a murine pemphigus mouse model, although the mechanism is not fully understood." (PMID 35844545, 2022). "We found that ADAM10 inhibition is protective against the pathogenic effects of pemphigus autoantibodies which primarily target Dsg3 but not Dsg1." (PMID 35844545, 2022). "To test whether the protective effect of ADAM10 inhibition depends on the amount of autoantibodies targeting Dsg3, we performed dissociation assays with AK23, a pathogenic monoclonal Dsg3 autoantibody derived from a pemphigus mouse model." (PMID 35844545, 2022). "Despite the relatively limited number of studies investigating the role of MMPs in autoimmune blistering diseases, inactivation of ADAM10 and MMP-9 were shown to prevent blister formation in experimental models of pemphigus and pemphigoid, respectively." (PMID 34680139, 2021). "Moreover, ADAM10 inhibition was shown to be protective in a murine pemphigus model when antibodies against Dsg1 and Dsg3, but not Dsc3, were present in the patient sera." (PMID 35844545, 2022). "However, the effect of ADAM10 appeared to depend on the antibody profile, because ADAM10 inhibition was not protective in both the cell culture and ex vivo pemphigus skin models, when a PV-IgG from a different patient (PV4-IgG), containing high levels of anti-Dsg1 autoantibodies was used." (PMID 35844545, 2022).
proliferative diabetic retinopathy (2 papers, 2020 to 2022). Advanced retinopathy due to diabetes mellitus characterized by the formation of new vessels in the retina. "We investigated the involvement of these chemokine pathways and their processing metalloproteinases ADAM10 and ADAM17 in the pathophysiology of proliferative diabetic retinopathy (PDR)." (PMID 33552057, 2020). "Comparisons of vascular endothelial growth factor (VEGF), CXCL16, CX3CL1, ADAM10 and ADAM17 levels in proliferative diabetic retinopathy (PDR) patients with or without active neovascularization and nondiabetic patients with rhegmatogenous retinal detachment (RD)." (PMID 33552057, 2020).
retinal degeneration (2 papers, 2022 to 2025). Degeneration of the retina. "All these evidences suggest that ADAM10 potentially regulates a spectrum of functions in ocular tissues and perturbations to its activity manifest as retinal degeneration and neovascularization." (PMID 36185601, 2022). "Further investigation into the TMEM97—| CTNND2 → ADAM10 pathway may lead to precise and actionable therapeutic strategies to treat retinal degeneration." (PMID 39995975, 2025).
staphylococcus aureus infection (2 papers, 2025 to 2026). An infectious process in which the bacteria Staphylococcus aureus is present. "The interaction of alpha-hydroxyprotein protein and its cell receptor ADAM10 (inducing rapid platelet aggregation) after Staphylococcus infection impures endothelial repair function, and promotes neutrophil inflammation signal transmission to form harmful platelet-neutrophil aggregation in organs." (PMID 40230845, 2025).
type 2 diabetes (2 papers, 2022). "In conclusion, serum concentration of ADAM10 is increased in type 2 diabetes and is associated with glycemia and insulin therapy." (PMID 35705192, 2022). "Serum concentration of ADAM10 is increased in type 2 diabetes and is associated with glycemia and insulin therapy, which may potentially affect the specificity of systemic ADAM10 level as a biomarker." (PMID 35705192, 2022). "We therefore firstly determined whether type 2 diabetes was associated with changes in serum ADAM10 levels and examined the effect of exogenous insulin therapy on ADAM10 levels." (PMID 35705192, 2022). "Our study is the first study investigating systemic levels of ADAM10 in people with type 2 diabetes." (PMID 35705192, 2022). "Moreover, we have shown that the observed increase in systemic ADAM10 level in type 2 diabetes was accompanied by changes in its substrate concentration, and serum ADAM10 level correlated with sLOX‐1 in our study." (PMID 35705192, 2022). "We have demonstrated that serum ADAM10 is increased in type 2 diabetes, but our study does not have sufficient power to investigate the relationship between diabetic vascular complications and ADAM10." (PMID 35705192, 2022). "Since high glucose can upregulate ADAM10 expression in vitro, we investigated whether serum levels of ADAM10 and its substrate, the lectin‐like oxidized low‐density lipoprotein receptor 1 (LOX‐1), can be influenced by type 2 diabetes." (PMID 35705192, 2022).
abscess (1 paper, 2018). An inflammatory process characterized by the accumulation of pus within a newly formed tissue cavity which is the result of a bacterial, fungal, or parasitic infection or the presence of a foreign body. "GO analysis with the unique differential promoters involved in Munro’s abscess formation revealed neutrophil and leukocyte chemotaxis as the highest enriched biological processes which include genes like HRH1, PDE4D, CCL25, AIF1, ADAM10, FFAR2, IL1B and TREM1." (PMID 30092825, 2018).
acute monocytic leukemia (1 paper, 2015). Acute monoblastic leukemia (AML-M5), is one of the most common subtypes of acute myeloid leukemia (AML) that is either comprised of more than 80% of monoblasts (AML-M5a) or 30-80% monoblasts with (pro)monocytic differentiation (AML-M5b). "Furthermore, the functional assay showed that ADAM10 C-A haplotype carriers exhibited significantly higher reporter activity compared with the T-A carriers and T-C carriers in human acute monocytic leukemia cell line." (PMID 25888255, 2015).